IL6 (interleukin 6)
Diseases named in the same sentence as IL6 in open-access papers (continued):
Sharing a sentence is not in itself a finding about the gene and the disease.
inflammation (continued). "Chronic inflammation has been shown to promote bone resorption, as inflammatory cytokines like tumor necrosis factor-alpha (-α), interleukin-6 (IL-6), and receptor activator of nuclear factor kappa-B ligand (RANKL) stimulate osteoclastogenesis." (PMID 40284258, 2025). "Chronic inflammation, marked by elevated cytokines like IL-6 and CRP, further suppresses albumin production and accelerates its breakdown." (PMID 40703630, 2025). "Inflammatory cytokines, such as tumor necrosis factor-alpha (TNF-α), interleukin-6 (IL-6), and IL-1β, which are elevated in chronic systemic inflammation, have been shown to promote microglial activation and shift them toward a pro-inflammatory phenotype." (PMID 40141084, 2025). "HH also caused cardiac inflammation and fibrosis, especially in the OVX + HH group, which had elevated proinflammatory cytokines (IL-1β, IL-6, TNF-α) and decreased anti-inflammatory cytokines (TGF-β, IL-10)." (PMID 40108505, 2025). "Previous research has shown that individuals with frailty exhibit elevated levels of inflammatory markers such as C-reactive protein (CRP), interleukin-1 beta (IL-1β), and IL-6, accompanied by chronic systemic inflammation and increased monocyte counts." (PMID 40697920, 2025). "TLR4 activation leads to increased expression of inflammatory genes such as NF-κB, Myd88, and CD14, resulting in the production of inflammatory cytokines (IL-1β, IL-6, TNF-α), which cause liver inflammation and damage." (PMID 40362886, 2025). "On the other hand, aging is associated with a decline in immune function, characterized by increased production of pro-inflammatory cytokines such as IL-6; this chronic inflammation has been shown to exacerbate age-related diseases." (PMID 40943361, 2025). "In an animal model of SSc, knocking out the IL-6 gene significantly reduced lung inflammation and collagen deposition in mice." (PMID 40843700, 2025). "Interleukin-6 (IL-6): a proinflammatory cytokine that plays a central role in post-injury immune activation and endothelial inflammation." (PMID 41010412, 2025). "Recent studies have indicated that GO can significantly diminish the production of the proinflammatory cytokines TNF-α, IL-1β, and IL-6 in LPS-induced macrophages or murine models, thereby reducing airway inflammation." (PMID 41562115, 2025). "Activated macrophages infiltrate RA patients’ synovial fluid and secrete pro-inflammatory cytokines (TNF-α, IL-1β, and IL-6), which in turn promote synovial inflammation and lead to cartilage and bone destruction, which correlates with the severity of RA." (PMID 38966637, 2024). "Systemic inflammation in CKD is common and increased serum inflammatory biomarkers like C-reactive protein (CRP), inter-leukin-6 (IL-6) and tumour necrosis factor (TNF) are associated with CVD and all-cause mortality." (PMID 38638550, 2024). "It is believed that IL-6 is produced through the activation of epithelial–macrophage crosstalk in the colon, triggered by gut inflammation and microbial dysbiosis." (PMID 38473999, 2024). "To further understand the role of inflammatory cytokines in AHL‐related cochlear inflammation, we used real‐time PCR to assess the expression of three key cytokines, IL‐6, IL‐1β, and TNF‐α, in the cochlea." (PMID 39148148, 2024). "IL-6, known for its pro-inflammatory properties, exacerbates OA by fostering synovial inflammation, cartilage breakdown, and catabolic processes within joints." (PMID 38794200, 2024). "IL-6 is one of the critical mediators that induces inflammation, and we previously reported that IL-6 gene deletion prevents cardiac inflammation, fibrosis, and dysfunction." (PMID 38495093, 2024). "For example, in primary cardiac cells, Cu2+ increases the release of interleukin-6 (IL-6) and activates MAP kinases, which are linked to cardiac inflammation and hypertrophy." (PMID 38218941, 2024).
inflammation (continued). "IL-6R expression was increased by 110% following lipid droplet accumulation, supporting a role of lipid droplet remodeling in overactive IL-6 trans-signaling-induced cardiac inflammation." (PMID 39063055, 2024). "As a pro-inflammatory factor, IL-6 is usually increased in response to liver inflammation, and it is generally considered to be a harmful cytokine." (PMID 39478979, 2024). "Previous studies have indicated that airway inflammation can lead to the release of pro-inflammatory cytokines such as IL-1β, IL-6 and TNF-α by the human broncho-epithelial cells and macrophages." (PMID 37851060, 2024). "On note, renal inflammation in ADPKD has been associated with the expression and accumulation of proinflammatory cytokines, including TNFα, IL-6, IL-8 and MCP1." (PMID 38732256, 2024). "LPS induced lung inflammation, as evidenced by increased IL-1β, IL-6 and TNF-α levels in the serum compared to those in the Sham group." (PMID 38802896, 2024). "Limited preclinical data are available for the impact of phospholipids on IL-6 and IL-8 secretion in animal models of liver inflammation." (PMID 38664334, 2024). "Simultaneously, the female immune system actively responds to acute WS exposure, resolves lung inflammation, and consequently leads to a significant decrease in the concentrations of IL-6 and IL-10 BAL cytokines." (PMID 38797836, 2024). "Chronic inflammation in the prostate can lead to an overproduction of growth factors, such as tumor necrosis factor-alpha (TNF-α) and interleukin-6 (IL-6), causing excessive prostate cell proliferation and remodeling." (PMID 38519941, 2024). "Studies on animal models have also shown that brain inflammation is inhibited in animals that have received FA due to the reductions in the expression of pro-inflammatory cytokines IL-6, IL-1β, and TNF-α." (PMID 37590236, 2023). "We found, however, that IL-6 and IL-6 signaling were dispensable for inhibiting lung Th2 cell accumulation and allergic eosinophilic inflammation in response to HDM contaminated with 400-fold higher levels of LPS (i.e., 0.4 mg LPS per 1 mg HDM; HDMLPS400)." (PMID 37046042, 2023). "In DSS-induced intestinal inflammation, mucosal Il6 and plasmatic SAA correlated positively with BLI, while Tgfb1 correlated negatively in the therapeutic approach." (PMID 37047397, 2023). "In vascular smooth muscle cells, induced by vasoconstrictor angiotensin II, RHOA mediates phospho-Ser536 nuclear factor κB/RelA subunit exchange on the IL-6 promoter, thereby mediates IL-6 expression and vascular inflammation." (PMID 37781036, 2023). "Meanwhile, the synthesis of a series of inflammatory mediators, IL-8 and IL-6, produces a powerful proinflammatory effect, leading to synovial inflammation, cartilage destruction, and bone erosion, thereby stimulating the proliferation of synovial fibroblasts." (PMID 35096114, 2022). "It has been reported that the occurrence of cognitive disturbances upon CNS inflammation has been correlated with increased levels of IL-6 and IL-1β." (PMID 35255943, 2022). "The levels of TNF-α, IL-6, and IL-1β in the EtOH group were remarkably higher than that in the Ctrl group (p < 0.001), indicating the occurrence of liver inflammation." (PMID 35681289, 2022). "Liver fat accumulation can promote the release of a variety of pro-inflammatory cytokines, such as tumor necrosis factor-α (TNF-α), interleukin-6 (IL-6), interleukin-1β (IL-1β), leading to liver inflammation and cellular damage." (PMID 35630624, 2022). "IL-6 plays a significant role in severe lung inflammation, and blocking IL-6 signaling improves the pulmonary outcome in several conditions." (PMID 36591278, 2022). "Our data showed higher levels of IL-6 in rhabdomyolysis and associated AKI, and this was consistent with glycerol triggered kidney inflammation." (PMID 35285384, 2022).
inflammation (continued). "Oxidative stress causes liver inflammation, leading to secretion of pro-inflammatory cytokines such as TNF-α, interleukin-1 beta (IL-1β) and interleukin-6 (IL-6)." (PMID 36358518, 2022). "Prolonged P. aeruginosa infections have been linked to chronic inflammation in the CF lung, whose hallmarks are increased levels of cytokines (i.e., TNF-α, IL-1β, IL-6) and neutrophil attraction by chemokines, like IL-8." (PMID 35903151, 2022). "Aberrant and excessive activation of some cytokines is involved in the pathogenesis of IBD, among which IL-1β and IL-6 have been regarded to play a prominent role in the initiation and maintenance of colonic inflammation, respectively." (PMID 35330829, 2022). "Detrusor muscles from CYP-treated mice displayed a significant increase in Il6 and Tnf (inflammatory markers) (n = 4) suggesting the onset of bladder inflammation after CYP treatment." (PMID 35332235, 2022). "RS provided also exerted a protective role against DSS-induced colonic inflammation as reflected by a decrease in colonic pro-inflammatory cytokine levels of IL-1β, IL-6, TNF-α, and IFN-γ in proximal or distal segments." (PMID 35836245, 2022). "IL-6 is known to be the first protective during acute cardiac inflammation, but excessive IL-6 during chronic inflammation leads to malignant effects on cardiac function." (PMID 35967380, 2022). "TNF-α and IL-6 are regarded as the major contributors to gastric inflammation and mucosal injury, and their serum levels are positively correlated with the severity of GU." (PMID 35140802, 2022). "Lack of STAT6 expression in KO mice induced more severe lung inflammation, associated with elevated neutrophil influx and expression of TNF-alpha, IL-6 and IL-1beta in the inflamed lung tissues." (PMID 35606692, 2022). "Previous studies have shown that IL-6 plays an important role in both primary and secondary storms; thus, inhibition of IL-6 has potential value in the treatment of lung inflammation/injury." (PMID 36215225, 2022). "IL-6, a typical cytokine for sustaining homeostasis, has a pathological effect on acute systemic inflammation once IL-6 level is excessively dysregulated and persistently synthesized." (PMID 35433741, 2022). "AS-IV improved endothelial function via the up-regulation of eNOS expression, alleviated oxidative stress via increasing antioxidant enzymes activities, and inhibited cardiac inflammation via down-regulating IL-6 and TNF-α expression." (PMID 34803698, 2021). "The ventilated Aoah-/- mice had more neutrophils and IL-6 in their airspaces as well as higher levels of lung inflammation than did Aoah+/+ control mice, especially when the mice had been instilled with HCl." (PMID 34783310, 2021). "In particular, the fetal inflammatory response syndrome is characterized by systemic inflammation and elevated fetal plasma IL-6 levels." (PMID 34046191, 2021). "TNF-α and IL-6 are important mediators of the immune response and chronic inflammation, and the gene promoter regions of both cytokines contain the NF-κB binding site." (PMID 34712822, 2021). "The hallmarks of CRS include high serum levels of proinflammatory cytokines and chemokines, especially the IL-1 family and IL-6, which initiate the inflammatory cascade resulting in lung inflammation, fever, and fibrosis." (PMID 34009133, 2021). "Intra-amniotic inflammation (IL-6 ≥ 2600 pg/ml) was diagnosed in 80% (8/10) of women who delivered within 24 h of amniocentesis and in 29% (8/28) of women who gave birth later in gestation." (PMID 34188072, 2021). "Pulmonary inflammation was also assessed by quantifying Il-6, Tnf, Cxcl2 and Cxcl5 mRNA expression levels in lung tissue." (PMID 34717665, 2021). "T2DM can induce liver inflammation evidenced by an increase of proinflammatory cytokines NF-κB, TNF-α, IL-6, and IL-1β, which is associated with cell apoptosis and oxidative stress, all factor promoting HCC progression." (PMID 35002979, 2021).
inflammation (continued). "LV gene expressions of pro-inflammatory cytokines, TNFα and IL-6, were significantly elevated in nicotine-administered rats compared to the vehicle controls (p < 0.05), indicative of cardiac inflammation." (PMID 34226619, 2021). "Pulmonary inflammation was significantly affected by acute inflammation, as demonstrated by immune cell infiltration and NF-kB target gene (IL-6, CRP, COX-2, SOD1) upregulation." (PMID 34086835, 2021). "Subsequently, the expression of molecules crucial for the development of vascular inflammation, including IL-6, MMP-2, MMP-9, VCAM-1, and ICAM-1, was measured." (PMID 34336088, 2021). "MCTs produce harmful volatile organic compounds and increase interleukin-8 (IL-8) and interleukin-6 (IL-6) levels which are biomarkers for lung inflammation and injury." (PMID 34778207, 2021). "Our results shown that PE effectively alleviate mammary inflammation by inhibiting the expression and secretion of IL-6, IL-1β, TNF-α in vivo and in vitro, and inhibiting the synthesis of iNOS and MPO." (PMID 34383710, 2021). "SARS-CoV-2 can trigger endothelial inflammation and the production and release of inflammatory cytokines such as IL-1β, TNFα, and IL-6." (PMID 34792686, 2021). "IL-6 is a proinflammatory cytokine that mediates acute lung injury, exacerbates ventilator-induced lung injury, and plays an essential role in lung inflammation in preterm newborns." (PMID 33506026, 2021). "IL-6 induced the expression of acute-phase proteins during acute inflammation, and the levels of TNF-α and IL-6 in serum and colon tissue closely correlate with the severity of intestinal inflammation." (PMID 35010176, 2021). "α-MG suppressed the brain levels of LPS-induced pro-inflammatory cytokine interleukin-6 (IL-6), cyclooxygenase-2, and 18 kDa translocator protein, a sensitive biomarker of brain inflammation." (PMID 32867357, 2020). "A reduction of IL-1β, TNF-α, and IL-6 and increased pulmonary inflammation was found when BCG was used to intravenously infect C57BL/6 diabetic mice." (PMID 32194998, 2020). "Mediators related to lung inflammation include tumor necrosis factor α (TNFα), interleukin-6 (IL-6), and interleukin-1β (IL-1β), which regulate maturation of dendritic cells and induce recruitment of neutrophils at inflammatory sites." (PMID 32752184, 2020). "Previous studies have shown that SiONPs exposure increases the production of TNF-α, IL-6, and IL-1β and elevates inflammatory cell recruitment into lung tissues, resulting in the aggravation of airway inflammation." (PMID 32164364, 2020). "Early studies on patients with SARS showed that elevation of proinflammatory cytokines such as IL-1β, IL-6, IL-12, IFN-γ, IP-10, and MCP-1 was associated with pulmonary inflammation and extensive lung damage." (PMID 32707537, 2020). "A study demonstrated that IL-6 was transmitted from the lungs to the systemic circulation, as shown by differences in arteriovenous IL-6 levels due to increased lung inflammation and simultaneous lung permeability." (PMID 32963734, 2020). "Elevated markers of systemic inflammation such as interleukin 6 drive vascular permeability and leakage, a key characteristic of patients with systemic inflammation, and are predictors of high mortality and poor neurological outcome." (PMID 31275944, 2019). "Whereas Treg development during experimental airway inflammation is controlled via membrane-bound IL-6R, IL-6 trans-signaling orchestrates T cell recruitment in an experimental peritoneal inflammation model." (PMID 31694340, 2019). "Since gut microbiota has been shown to mediate systemic chronic inflammation in various diseases, we next analyzed potential correlations between the differentially abundant fecal microbiota and the inflammatory factors IL-4, IL-6, and IL-10." (PMID 31245306, 2019). "Our results show that PO suppresses lung inflammation by the reduction of IL-β, IL-6, TNF-α, PGE2, and TGF-β, as well as by the increase of IL-10 levels." (PMID 30609661, 2019).
inflammation (continued). "Treatment with a selective COX-2 inhibitor, SC-58125, reduced synovial inflammation by reducing local and systemic IL-6 levels, thus reversing paw edema in adjuvant-induced arthritis rat model showing regulation of IL-6 by COX-2-derived PGs." (PMID 31666079, 2019). "Proinflammatory cytokines, such as TNF-α, IL-6, which are released from activated microglia are considered to play important roles in the pathogenesis of neuro-inflammation in the CNS." (PMID 30400195, 2018). "In the murine subcutaneous air pouch model of acute gouty inflammation, arhalofenate significantly inhibited leukocyte or neutrophil infiltration and production of IL-1β, IL-6, and CXCL1 induced by MSU crystals." (PMID 30189890, 2018). "A longer duration of CPB goes along with higher risk for renal ischemia and causes renal inflammation by inducing an increase in cytokines such as TNF-α, IL-1 and IL-6." (PMID 29973162, 2018). "Another study in zymosan-induced acute peritoneal inflammation demonstrated that IL-6 gene deletion inhibits the development of organ failure." (PMID 30142934, 2018). "Our previous work have demonstrated that depletion of B cells with anti-mouse CD20 resulted in significant elevation in IL-6, amelioration of liver inflammation but exacerbation of colon inflammation." (PMID 30450101, 2018). "IL-6 is another important proinflammatory cytokine, being a vital Th2 cytokine involved in the pathological process of pulmonary inflammation." (PMID 30305831, 2018). "And this leads to a decline of proinflammatory cytokines, including TNF-a, IL-8 and IL-6, and in turn reduces the incidence of postoperative hepatic inflammation." (PMID 30006616, 2018). "As a result of cardiac inflammation, the IL6, TNFα and MCP1 transcription levels were also higher in post-infarcted myocardium, and this effect was inhibited by Mst1 knockout." (PMID 29760744, 2018). "We believe that these IL-1β-expressing cells participate in the sensing of injury generated by lung IR and trigger the cascade of events leading to mature IL-1β release, IL-6 production, neutrophil recruitment, and overall lung inflammation." (PMID 29163464, 2017). "Compared to FRA exposed mice, Al2O3 NPs-exposed mice had higher concentrations of bronchoalveolar lavage fluid (BALF) interleukin (IL)-6 (a cytokine associated with decline in lung function) and BALF IL-33 (a cytokine induces chronic airway inflammation)." (PMID 29233151, 2017). "Intra-amniotic infection was defined as a positive AF culture for microorganisms and intra-amniotic inflammation was defined as elevated AF concentrations of IL-6 or IL-8 (IL-6 ≥1.5 ng/mL and/or IL-8 ≥1.3 ng/mL)." (PMID 28358839, 2017). "In agreement with our previous studies, the combined fracture and thoracic trauma resulted in a pulmonary inflammation in WT mice, as confirmed by increased C3a, IL-6 and chemokine (C-X-C motif) ligand 1 (CXCL1) concentrations 21,24." (PMID 29070810, 2017). "AngII infusion resulted in renal inflammation, highlighted by increased interleukin-6 and tumor necrosis factor-α concentrations, which were abolished by the αAnalogue." (PMID 28446517, 2017). "Previous studies identified NF-κB as the central transcription factor mediating IL-6 expression during vascular inflammation." (PMID 28467355, 2017). "Experimental blockade of IL-6 signaling with monoclonal antibodies was effective in suppressing chronic intestinal inflammation in mouse models, which suggests IL-6 as a potential therapeutic target in management of IBD." (PMID 28770521, 2017). "Previous studies have shown that nerve inflammation and nerve injury caused rapid activation of spinal microglia and elevated expression of TNF-α, IL-1β, and IL-6, which promoted the nociceptive transmission in the spinal cord." (PMID 26064176, 2015).